CGAS (cyclic GMP-AMP synthase)
Diseases named in the same sentence as CGAS in open-access papers (continued):
Sharing a sentence is not in itself a finding about the gene and the disease.
HIV-1 infection (22 papers, 2014 to 2026). The type species of lentivirus and the etiologic agent of acquired immunodeficiency syndrome (AIDS). "Recently, it was shown that the cytosolic DNA sensor cGAS is also implicated in sensing HIV-1 infection in activated CD4+ T cells." (PMID 31968566, 2020). "This will provide a critical basis for understanding the role of the cGAS-STING pathway in vivo during HIV-1 infection and help bridge the gap between in vitro findings and clinical observations." (PMID 41373786, 2025). "Multiple innate immune sensors can contribute to IFN and inflammation during HIV-1 infection, but cGAS activation is increasingly appreciated as a driver of protective anti-HIV immune responses." (PMID 39874383, 2025). "Recently, PQBP1 has been identified as an indispensable cellular factor of a priming event for recognition of HIV-1 infection by the cGAS–STING pathway, accentuating PQBP1’s role in inflammation and in innate immune response regulation." (PMID 39205314, 2024). "The phosphorylation enhances the binding of PQBP1 and cGAS and the oligomerization of cGAS, leading to an enhanced innate response upon HIV-1 infection." (PMID 39205314, 2024). "Recent work has suggested that an additional factor, polyglutamine-binding protein 1 (PQBP1), helps to license cGAS activity during HIV-1 infection, through its capacity to link cGAS to the viral capsid." (PMID 38712059, 2024). "Here, we demonstrate that the activation of a second signaling pathway enables a cyclic GMP-AMP synthase (cGAS)-dependent type I interferon (IFN-I) response to HIV-1 infection." (PMID 34844429, 2021). "In this work, we demonstrated that TLR signaling cooperates with the cGAS-STING pathway to enable HIV-1 infection to stimulate a type I IFN response in macrophages." (PMID 34844429, 2021). "The specific relevance of cGAS-STING signaling in sensing of HIV-1 infection in infected pDCs is still unclear, although human pDCs harbor a functional cGAS-STING pathway." (PMID 31968566, 2020). "It was identified as a proximal sensor of cGAS-mediated signaling in response to HIV-1 infection through a targeted RNAi screen in MDDCs." (PMID 31968566, 2020). "In MDDCs and macrophages, HIV-1 infection induces a robust IFN response in a manner dependent on the cGAS-STING pathway." (PMID 31968566, 2020). "The addition of viral-like particles (VLPs) carrying Vpx enhances HIV-1 infection and promotes cGAS-dependent innate immune response through degradation of SAMHD1 and possibly other undefined mechanisms." (PMID 31968566, 2020). "cGAS-STING signaling has been considered a major sensing pathway to mount the antiviral immune response in the context of HIV-1 infection." (PMID 31968566, 2020). "Another cytosolic DNA sensor, cyclic GMP-AMP synthase (cGAS), is widely known for its antiviral immunity in the context of HIV-1 infection." (PMID 33343516, 2020). "Significantly, Vpr interaction with CRL4DCAF1 E3 has been genetically linked to its effects on DNA damage checkpoint activation and innate sensing of HIV-1 infection via the cytosolic DNA sensor cyclic GMP-AMP synthase (cGAS)." (PMID 30352932, 2018). "Silencing of cGAS drastically impaired the induction of both IFNα and IFNβ secretion in response to HIV-1 infection." (PMID 26067651, 2015). "Our experiments in more physiologic primary cDCs from EC demonstrated that HIV-1 infection led to a rapid induction of cGAS expression, and cGAS silencing in primary cDCs effectively inhibited type I IFN secretion." (PMID 26067651, 2015). "The presence of single-stranded DNA in the cytosol during the early stages of HIV-1 infection could potentially engage multiple DNA sensors as well as cGAS, collectively contributing to the immune response against the virus." (PMID 38530250, 2024).
HIV-1 infection (continued). "These factors encompass an elevated vector dose exceeding the initial dosage administered during HIV-1 infection, loss of viral accessory proteins that aid in immune evasion during HIV-1 infection, and the stimulation of the cGAS pathway through the presence of DNA within the vector." (PMID 37766208, 2023). "HIV-1 infection per se is ineffective for activating cGAS-mediated IFN-I responses." (PMID 34844429, 2021). "Therefore, in this section, we will elaborate on the mechanisms regulating cGAS-STING signaling activation in response to HIV-1 infection." (PMID 31968566, 2020). "In addition to these positive regulators required for cGAS-STING signaling activation in response to HIV-1 infection, several host factors were reported to negatively regulate cGAS-mediated signaling in the context of HIV-1 infection." (PMID 31968566, 2020). "However, these cGAS regulating mechanisms have been poorly characterized in the context of HIV-1 infection." (PMID 31968566, 2020). "However, the role of cGAS in natural HIV-1 infection of primary target cells such as macrophages and DCs, which are not activated upon virus entry, and the evasion strategies employed by the virus, have not been investigated in detail." (PMID 24782340, 2014). "During HIV-1 infection, ISG15 promotes the ISGylation of STING—a covalent attachment of ISG15 to the target protein—that facilitates STING oligomerization and enhances cGAS-STING pathway activation." (PMID 41373786, 2025). "This is the prerequisite for efficient interferon-stimulated gene (ISG) induction upon HIV-1 infection, highlighting the importance of PQBP1 as a co-sensor of the cGAS–STING pathway and its emerging role in innate immunity." (PMID 39205314, 2024). "Cross-talk between cGAS and TLR signaling pathways enables type I IFN induction upon HIV-1 infection." (PMID 34844429, 2021). "When humans are infected with HIV-1, at least two PRRs, CGAS and IFI16, sense HIV-1 infection and induce IFN-I production." (PMID 30915053, 2019). "These experiments revealed that cGAS is essential for DC activation after HIV-2, HIVac-2 and HIV-1 infection in the presence of Vpx." (PMID 24782340, 2014). "Furthermore, this observation aligns with previous studies demonstrating that DCs restrict productive HIV-1 infection through multiple mechanisms, including SAMHD1-mediated dNTP depletion, cGAS sensing, and other intrinsic antiviral defenses." (PMID 41596493, 2026). "During HIV-1 infection, PQBP1 relocates next to the viral cores in the cytoplasm, where it interacts with the intact HIV-1 capsid, binding in the region of the central pore, and stimulates cGAS recruitment onto viral cDNA during capsid disassembly." (PMID 41373786, 2025). "To summarize the findings presented above, we can confidently state that the activation of the cGAS-STING pathway in response to HIV-1 infection occurs not only in model cell lines but is also observed directly in HIV-infected patients." (PMID 41373786, 2025). "As expected, HIV-1 infection was blocked by LEN treatment (10 nM), but was not affected by loss of cGAS, STING, or IRF3." (PMID 38712059, 2024). "One question that has been raised is why interferons (IFNs) are not strongly induced through cGAS (cyclic GMP-AMP synthase) sensing in the cytoplasm of the cell during the early stages of HIV-1 infection." (PMID 33572761, 2021). "Moreover, cGAS is involved in sensing of reverse transcribed DNA products and IFN induction during HIV-1 infection in cell lines 75,76." (PMID 24782340, 2014). "HIV-1 infection by itself is not a potent stimulus that initiates cGAS-dependent IFN-I signaling." (PMID 34844429, 2021). "However, during HIV-1 infection NONO (Non-POU Domain Containing Octamer Binding) protein binds to its capsid and activates cGAS signaling along with inducing cGAS association with the HIV DNA in the nucleus." (PMID 33643304, 2020).
HIV-1 infection (continued). "Among all of the well characterized cGAS regulators, polyglutamine binding protein-1 (PQBP1) and Non-POU (Pit-Oct-Unc) domain-containing octamer-binding protein (NONO) are the only host factors currently known to specifically regulate cGAS-mediated innate sensing of HIV-1 infection." (PMID 31968566, 2020). "Consequently, NLRC3 might be involved in modulating cGAS/STING signaling during HIV-1 infection, although it is currently not known if HIV DNA binds to NLRC3 and promotes its dissociation from STING." (PMID 31968566, 2020). "Moreover, during HIV-1 infection of primary CD4+ T cells, it has been reported that either cGAS is not essential for IFN induction, or significant IFN levels are not even induced." (PMID 31968566, 2020).
liver fibrosis (21 papers, 2021 to 2025). "In mice, Xbp1 deficiency ameliorates liver fibrosis by reducing the cytosolic release of mtDNA owing to oxidative mitochondrial injury to suppress NLPR3 activation in a cGAS-STING IRF3-dependent manner." (PMID 39183465, 2024). "Atractylenolide III (ATR III) mitigates liver fibrosis by suppressing the cGAS/NF-κB pathway in HSCs, which subsequently inhibits the senescent cell-derived senescence-associated secretory phenotype (SASP) and decreases inflammation." (PMID 41041344, 2025). "The release of leaked dsDNA subsequently activated the cGAS-STING pathway, leading to the release of secretion factors associated with the SASP, HSC senescence, and ultimately attenuated liver fibrosis." (PMID 40860128, 2025). "Accumulating evidence underscores the pivotal yet complex role of the cGAS-STING pathway in liver fibrosis, primarily through two interconnected mechanisms: the direct activation of HSCs and the amplification of immune-driven profibrotic responses." (PMID 41438738, 2025). "Our previous study demonstrated that OA activates the cyclic GMP-AMP synthase (cGAS)-stimulator of interferon genes (STING) pathway to induce HSC senescence against hepatic fibrosis." (PMID 40777599, 2025). "Background and aims: Inducing the senescence of activated hepatic stellate cells (HSCs) has emerged as a promising therapeutic strategy for liver fibrosis, with potential connections to the Yes-associated protein (YAP)-controlled cGAS-STING pathway." (PMID 40860128, 2025). "Oroxylin A induces HSC senescence during liver fibrosis, both in vitro and in vivo, by activating the cGAS-STING pathway, which is mainly offset by DNMT3A overexpression." (PMID 39183465, 2024). "Recent studies have shown that the cGAS-STING pathway plays an important role in the pathological process of liver fibrosis, and various traditional Chinese medicines can exert anti-fibrotic effects by regulating this pathway." (PMID 39737190, 2024). "In chronic CCl4-induced liver fibrosis in mice, induction of cGAS-STING signalling promotes the dysfunction of LSECs to increase sinusoidal microthrombosis, which results in increased portal vein pressure, thus aggravating the degree of fibrosis." (PMID 39183465, 2024). "In mice with hexafluoropropylene oxide trimer acid (HFPO-TA)-induced liver fibrosis, mitochondrial ROS (mtROS) production was increased, inducing cGAS-STING signalling as an upstream regulatory mechanism of pyroptosis and fibrosis." (PMID 39183465, 2024). "In summary, the cGAS-STING pathway orchestrates liver fibrosis through a dual-pronged mechanism: it directly transduces profibrotic signals in HSCs and simultaneously amplifies a damaging inflammatory cascade across hepatocytes, immune cells, and endothelial cells." (PMID 41438738, 2025). "Furthermore, oroxylin A induces cGAS-STING pathway to stimulate cytokines such as IFNβ to activate ferritinophagy to prevent liver fibrosis." (PMID 39183465, 2024). "HFPO-TA promotes liver fibrosis through mtROS/cGAS-STING/NLRP3-induced pyroptosis." (PMID 39183465, 2024). "Increasing evidence indicates that the cGAS-STING pathway influences liver fibrosis." (PMID 39183465, 2024). "Additionally, we showed that cGAS regulates liver fibrosis in a STING-type I–IFN-independent manner." (PMID 35108342, 2022). "Importantly, cGAS exacerbates Schistosoma infection by promoting the formation of granulomas and boosting liver fibrosis in both STING-dependent and -independent manners." (PMID 35108342, 2022). "Likewise, recent studies also show that X-box binding protein 1 (XBP1) regulates STING signaling and the subsequent NLRP3 activation during liver fibrosis, suggesting that macrophage self-mtDNA cytosolic leakage activates cGAS/STING/NLRP3 pathway providing a novel target against liver fibrosis." (PMID 36430874, 2022). "Moreover, we revealed a hitherto unknown role of cGAS in the regulation of liver fibrosis during Schistosoma infection, a process that is independent of STING." (PMID 35108342, 2022).
liver fibrosis (continued). "Through the cGAS-STING pathway, Oroxylin A from Scutellaria baicalensis affects ferroptosis-induced HSC aging, helping to ease liver fibrosis." (PMID 41041344, 2025). "Loss of myeloid XBP1 impairs BNIP3‐mediated mitophagy and promotes macrophage cGAS/STING/NLRP3 activation through leakage of mtDNA into the cytosol, thereby exacerbating liver fibrosis." (PMID 40211890, 2025). "Shaoyao Gancao Decoction (SGD) inhibits the liver cGAS-STING signaling pathway, thereby reducing HSCs activation and ultimately delaying the progression of AIH-related liver fibrosis." (PMID 41438738, 2025). "Our previous study found that S. baicalensis-derived OA is able to induce HSC senescence by stimulating the cGAS-STING pathway, thus inhibiting hepatic fibrosis." (PMID 40777599, 2025). "In mouse NASH models, licorice extract has the ability to hinder cGAS-STING pathway by suppressing STING oligomerization, thus alleviating hepatic fibrosis." (PMID 39183465, 2024). "In the CCl4 mouse liver fibrosis model, TDP-43 expression progressively increases along with activation of cGAS-STING signalling and an increase in inflammatory factors upregulated through the NF-κB pathway." (PMID 39183465, 2024). "It reduces inflammatory factors secreted by hepatic stellate cells by inhibiting the cGAS-STING pathway, thereby alleviating liver fibrosis." (PMID 39737190, 2024). "Interestingly, cGAS-STING signaling was shown to enhance hepatocyte pyroptosis and hepatic inflammation in liver fibrosis through activation of NLRP3 inflammasome." (PMID 40621423, 2025). "Interestingly, oroxylin A activates ferritinophagy through upregulation of the cGAS-STING pathway and accelerates HSCs senescence, thus suppressing liver fibrosis." (PMID 40621423, 2025). "Studies have shown that BEVs of intestinal flora origin can activate the cGAS/STING signaling pathway by carrying flora-originated DNA, which induces the secretion of pro-fibrotic and pro-inflammatory proteins from HSCs and aggravates hepatic fibrosis." (PMID 40621163, 2025). "Here, we demonstrated a novel function of cGAS in promoting liver fibrosis during schistosome infection, independent of STING, further proving the uncoupled functions of cGAS and STING in multiple biological processes." (PMID 35108342, 2022). "Oroxylin A stimulates cGAS-STING pathway to enhance the secretion of cytokines such as IFNβ, leading to upregulation of NCOA4 and subsequent regulation of ferritinophagy, indicating that the cGAS-STING pathway regulation of HSC senescence is a potential target for liver fibrosis therapy." (PMID 39183465, 2024). "This crucial study confirmed that the activation of the cGAS/STING pathway initiated the downstream cascade reaction, and NF-κB was translocated into the nucleus and upregulated pro-inflammatory cytokines expression, thus facilitating liver fibrosis eventually." (PMID 36818296, 2023). "The inhibitory or activating effect of the cGAS-stimulator of interferon genes (STING) pathway plays a vital role in the occurrence and development of non-alcoholic fatty liver disease (NAFLD), alcoholic liver disease (ALD), viral hepatitis, liver fibrosis, liver cancer and other liver diseases." (PMID 34386500, 2021). "Furthermore, evidence suggests that cGAS exerts functions independent of STING in promoting liver fibrosis, indicating that the roles of cGAS and STING may be uncoupled in various biological processes." (PMID 41438738, 2025). "Notably, future studies should also assess animal body weight, liver fibrosis scores, and standard blood markers of MASLD in our current mouse models, as well as determine whether ALDH2 inhibition or genetic ablation in hepatocyte‐specific cGas knockout mice can reverse HFD‐induced MASLD." (PMID 41042077, 2025). "Considering that cGAS, but not STING, promotes S. japonicum infection-induced liver fibrosis, we then investigated whether IFNβ affects this process." (PMID 35108342, 2022).